NF1 (neurofibromin 1)
Diseases named in the same sentence as NF1 in open-access papers (continued):
Sharing a sentence is not in itself a finding about the gene and the disease.
cutaneous melanoma (continued). "The Cancer Genome Atlas Network classifies cutaneous melanoma into four molecular subtypes based solely on genetic variation: BRAF-mutant (52%), RAS-mutant (28%), NF1-mutant (14%), and triple wild-type (6%)." (PMID 41001300, 2025). "In cutaneous melanoma, the most frequently genetic subtypes are mutant serine/threonine-protein kinase B-raf (BRAF) and GTPase NRas (NRAS), neurofibromin 1 (NF1) and triple wild-type." (PMID 41197182, 2025). "One of these genes was NF1, one of the MAPK pathway genes used to define the cutaneous melanoma genomic subtypes." (PMID 38758740, 2024). "Of the cutaneous melanoma samples, 81, 55, 19, and 20 samples were BRAF-, (N)RAS-, or NF1-mutant or TWT, respectively." (PMID 38758740, 2024). "The hyperactivation of PAK1 in cutaneous melanomas may be further attributed to activating mutations in RAC1, but also to even more common activating mutations in NRAS and the inactivation of RAS inhibitor NF1, as RAS-induced transformation involves and depends on the activation of RAC1 and PAK1." (PMID 37830586, 2023). "In this regard, the Cancer Genome Atlas (TCGA) program has established a framework of genomic classification for cutaneous melanomas as BRAF, NRAS, NF1, and Triple Wild-Type (WT), and serves as a guide when making decisions about therapy." (PMID 35844619, 2022). "The main genetic drivers for cutaneous melanoma are B-Raf proto-oncogene (BRAF), neurofibromin 1 (NF1), and neuroblastoma RAS viral oncogene homolog (NRAS) mutations, which are primarily mutually exclusive in primary tumours." (PMID 35884596, 2022). "Overall, alterations in BRAF, NRAS, NF1 and KIT are present in 93% of human cutaneous melanomas in a mutually exclusive pattern, although a small fraction of tumors harbor alterations in several of these genes." (PMID 35234863, 2022). "As an example, based on exome and genome sequencing studies, the TCGA Network has classified cutaneous melanoma into four distinct molecular subtypes: BRAF-mutant, NRAS-mutant, NF1-mutant, and BRAF/NRAS/NF1 wild-type (triple-wild-type group)." (PMID 34123788, 2021). "The Cancer Genome Atlas (TCGA) Network classified cutaneous melanoma into BRAF, NRAS (NRAS proto-oncogene), NF1 (neurofibromin 1), and triple-wild-type groups." (PMID 32344828, 2020). "According to the report, cutaneous melanoma can be classified into four subtypes: mutant BRAF; mutant NRAS; mutant NF1; and the triple-wild-type, which is characterized by a lack of hot-spot BRAF, N/H/KRAS, or NF1 mutations." (PMID 32028967, 2020). "The Cancer Genome Atlas (TCGA) allowed the identification of four genetic subtypes of cutaneous melanoma, BRAF mutant (the most common condition responsible for more than 50% of cases), RAS mutant, NF1 mutant, and Triple Wild-Type." (PMID 28118616, 2017). "This panel included cell lines representing all four molecular subtypes of cutaneous melanoma with driver mutations in the BRAF, NRAS, or NF1 genes and a fourth triple wild-type subtype, in which none of these genes are mutated." (PMID 37803324, 2023). "Although these tumors did not originate from the uvea of the eye, B16-F10 cells resemble UM in that they are immunotherapy-resistant, do not harbor classical cutaneous melanoma BRAF, NRAS, or NF1 mutations and the TMB is low." (PMID 34753889, 2022). "The majority (47.6%) of the acral melanoma patients did not exhibit mutations in BRAF, NRAS or NF1, and a substantial portion (28.6% compared to 5.6% in BCH-cutaneous melanoma, p = 2.28e−05) presented a pigmented skin phenotype." (PMID 35840550, 2022). "It is estimated that about a third of cutaneous melanomas are triple-negative and have no BRAF, NRAS, or NF1 mutations." (PMID 35008286, 2021).
cutaneous melanoma (continued). "Great support in this direction has been given by the exome sequencing studies of the Cancer Genome Atlas Skin Cutaneous Melanoma (SKCM-TCGA) project that classified cutaneous melanoma into four distinct molecular subtypes: BRAF-mutant, NRAS-mutant, NF1-mutant, and triple-wild-type group." (PMID 34944843, 2021). "Cutaneous melanoma is divided into four genomic subtypes: BRAF, NRAS, NF1, and Triple-WT." (PMID 33918490, 2021). "Four major genomic subtypes in cutaneous melanoma are BRAF, RAS, NF1, and triple wild-type." (PMID 33256089, 2020). "And also, among human cutaneous melanomas, there is a subgroup characterized by the lack of the most common recurring mutations of BRAF, N/H/K-RAS, or NF1, which are referred to as “triple negative” or “triple wild-type” subtype." (PMID 29534457, 2018). "There is also a subgroup of cutaneous melanomas characterized by a lack of BRAF, N/H/K-RAS, or NF1 mutations, which are referred to as the triple wild-type (TWT) subtype." (PMID 29385676, 2018). "Four major genetic subtypes of cutaneous melanoma have been proposed by The Cancer Genome Atlas according to frequently detected hot-spot mutations: mutant BRAF, mutant RAS, mutant NF1, and triple wild-type (TWT), characterized by a lack of BRAF, RAS, or NF1 mutations." (PMID 37239381, 2023).
optic pathway glioma (83 papers, 2005 to 2025). Optic pathway glioma (OPG) is a benign tumor that develop along the optic nerve (chiasm, tracts, and radiations) characterized by impairment or loss of vision and may be accompanied by diencephalic symptoms such as reduced growth and alteration in sleeping patterns. "Neurofibromatosis type 1 (NF1) gene mutations contribute to low-grade gliomas affecting the optic nerve (optic pathway gliomas) in early childhood." (PMID 40345526, 2025). "While NF1 is traditionally associated with optic pathway gliomas and other neoplasms, the emergence of PitNETs in these patients adds a layer of clinical and genetic complexity." (PMID 39968302, 2025). "An increased risk of neoplasia is typical for the disease, and among NF1-dependent tumors, one of the most common are optic pathway gliomas (OPGs)." (PMID 40361331, 2025). "Light exposure has been shown to stimulate the development of optic pathway gliomas, with NF1 mutation increasing NLGN3 shedding by ADAM10, and drives their progression." (PMID 40345526, 2025). "Though most of these differences were in cancers originating in the central nervous system such as optic pathway gliomas, it was possible that a similar Nf1-associated mechanism was promoting the earlier tumorigenesis in female P7NI mice." (PMID 36826025, 2023). "Apart from nerve sheath tumors, NF1 puts affected children at risk of many other nervous system and non-nervous system problems such as long-bone dysplasia, autism, optic pathway glioma, and pheochromocytoma." (PMID 37181996, 2023). "While pilocytic astrocytomas and optic pathway glioma generally arise spontaneously, a significant portion of optic pathway gliomas result from NF1 mutations." (PMID 37213290, 2023). "Up to 50% of optic pathway glioma arise in association with Neurofibromatosis type 1 (NF1), which affects 1 in 3,000 births and is a cancer predisposition syndrome." (PMID 37033188, 2023). "In a genetically engineered mouse model of NF1-associated optic pathway glioma, tumor growth was shown to be dependent on light exposure of the retina of the growing rodent; light deprivation prevented tumor formation and maintenance." (PMID 37511496, 2023). "Patients with NF-1 are at risk of developing optic pathway glioma, which usually involves tumor growth during childhood but not during adult life." (PMID 34828788, 2021). "This case describes the associated imaging findings in addition to a discussion of management and overall prognosis of sporadic compared to NF-1-associated optic pathway gliomas." (PMID 34646624, 2021). "In summary, this is the first reported case of concurrence of a truncated NF1 mutation with optic pathway gliomas and a nonsense PKD2 mutation." (PMID 32533764, 2020). "Conclusión: this is the first reported case of concurrence of a truncated NF1 mutation with optic pathway gliomas and a nonsense PKD2 mutation." (PMID 32533764, 2020). "In the context of optic pathway glioma, another NF1-associated benign tumor, Nf1+/− microglia (macrophage-like cells) enable tumor growth." (PMID 30479396, 2018). "An analysis of risk factors confirmed the improved outcome for patients with neurofibromatosis type 1 (NF1)-associated visual pathway glioma (NF1-VPG), whereas NF1-negative patients had a higher risk for progression after stopping chemotherapy." (PMID 28649001, 2017). "Other features that make up the diagnostic criteria include first degree family relative of NF-1, Lisch nodule of iris, axillary or groin freckling, optic pathway glioma, bony dysplasia of the sphenoid bone, and pseudoarthrosis." (PMID 23573448, 2013). "Patients with NF1 are at an increased risk of developing central nervous system tumors, including optic pathway gliomas and brainstem and cerebellar tumors." (PMID 16042772, 2005).
optic pathway glioma (continued). "It was found that 50%–70% of hypothalamic/optic pathway gliomas in the pediatric population are associated with NF1, an autosomal dominant disorder characterized by loss-of-function mutation in the NF1 gene, a negative regulator of the mitogen-activated protein kinase (MAPK) pathway." (PMID 37519792, 2023). "In addition to iris Lisch nodules, optic pathway glioma constitutes a part of the NF1 diagnostic criteria." (PMID 37181996, 2023). "Most patients with NF1-associated hypothalamic/optic pathway gliomas arise in children younger than 7 years and may regress spontaneously without treatment." (PMID 37519792, 2023). "Additionally, Neurofibromatosis 1 (NF1) mutation was reported to develop optic pathway gliomas, which leads to permeant blindness." (PMID 34980273, 2022). "In view of NF1-related puberty manifestations, adolescent children must be assessed for abnormal growth acceleration or early development of secondary sexual characteristics that may be linked to an optic pathway glioma involving the chiasma." (PMID 39257551, 2024). "Herein, we implemented a head-to-head preclinical strategy using a well-characterized murine model of NF1-optic pathway glioma (Nf1OPG)." (PMID 41497446, 2025). "Clinically, this case highlights that children with NF1 benefit from regular, age-appropriate ophthalmic surveillance with careful attention to optic pathway gliomas through visual examinations, behavioral assessments, and targeted imaging when indicated." (PMID 41341331, 2025). "The following therapeutic options are recommended as second-line therapy for pediatric patients with NF1 and the presence of recurrent or refractory optic pathway gliomas: vinblastine, carboplatin, vinorelbine, or bevacizumab, isolated or in combination." (PMID 41440192, 2025). "Bilateral optic pathway gliomas, which are considered pathognomonic for NF1, were found in 9.4% of our cohort of patients." (PMID 38893021, 2024). "Nearly 90% of the neuro-radiological characteristics were consistent with those of NF1, 52% of the patients had one or multiple types of tumors, and 34% had optic pathway glioma and were malignant." (PMID 39257551, 2024). "JPA has an association with Neurofibromatosis 1 (NF1), with afflicted patients being susceptible to other tumors including low-grade gliomas (LGG) in the optic nerve, commonly referred to as optic pathway gliomas (OPG)." (PMID 36549282, 2023). "In this cohort of Saudi pediatric patients with NF1, optic pathway glioma and other brain tumors were prevalent." (PMID 37181996, 2023). "The current study expected, even in these young ages, that the clinical features including axillary freckling, optic pathway gliomas, and NF1+ evolved as age increases." (PMID 35093157, 2022). "Histologically, these tumors represent pilocytic astrocytomas (WHO grade I) in the majority of NF1 patients and are termed optic pathway gliomas (NF1 + OPGs)." (PMID 34994964, 2022). "Optic pathway gliomas (OPGs) are a classic pathology seen in patients with neurofibromatosis I (NF-1); however, they are frequently seen as sporadic masses in patients with mutations activating the mitogen-activated protein kinase (MAPK) pathway." (PMID 34646624, 2021). "Mutations in this domain are found in a higher proportion of NF1 patients with optic pathway glioma." (PMID 35008787, 2021). "Around 6% of all NF-1 patients develop optic pathway glioma (OPGs), with a peak of incidence at the age of 3–4 years." (PMID 34828788, 2021). "We present a series of six pediatric patients with NF‐1 treated with trametinib for large, symptomatic, progressive PNFs, or refractory progressive symptomatic optic pathway gliomas." (PMID 33939292, 2021). "In another study investigating the natural history of FASI, optic pathways gliomas were present in 33% of 46 patients with NF1." (PMID 30410779, 2018).
optic pathway glioma (continued). "In patients with NF1, optic pathway gliomas are typically low-grade pilocytic astrocytomas and grow more insidiously, leading to a better prognosis than in other patients." (PMID 24711935, 2014). "Background/Aim: Among NF1-dependent tumors, the most common are optic pathway gliomas (OPGs)." (PMID 40361331, 2025). "Moreover, the frequency of axillary freckling, optic pathway glioma, and NF1+ significantly increased (P < 0.05)." (PMID 35093157, 2022). "Although the cell of origin for human pediatric LGGs is currently unknown, murine Nf1 LGGs of the optic nerve/chiasm (optic pathway gliomas; OPGs) arise from neural stem or neuroglial (progenitor) cells." (PMID 35986378, 2022). "Our study specifically excluded NF1 patients with optic pathway gliomas." (PMID 34727946, 2021). "The NF1 minipig develops optic pathway glioma and offers an ideal platform for these studies." (PMID 33978635, 2021). "In this report we highlight a case of a 38 year-old woman with an NF1 associated left chiasmal and optic tract glioma who had normal visual fields and visual acuity." (PMID 32351443, 2020). "A conditional NF1 deletion in neuroglial progenitor cells (Nf1+/–GFAP conditional knockout mice) was originally developed to model optic pathway gliomas, but these mice also display attention and memory deficits that result from reduced striatal dopamine levels." (PMID 31600280, 2019). "For instance, visual impairment was due to refraction problems in one individual and not caused by a co-existing NF1 related optic pathway glioma." (PMID 28193237, 2017). "In addition to the critical contributions from immune system cells, we have recently shown that NF1 mutation in neurons synergizes with light-induced retinal ganglion cell activity to regulate neuroligin-3 (NLGN3) shedding and Nf1-optic pathway glioma (Nf1-OPG) initiation and growth." (PMID 35589737, 2022). "In the current study, the association between radiological findings and the NF1 functional domain affected by mutations were newly revealed in young pediatric patients because of high FASI frequency and radiologic progression which included newly developed optic pathway glioma, PN, and tumors." (PMID 35093157, 2022). "NF1: neurofibromatosis type 1; OPG: optic pathway glioma; RT: radiotherapy." (PMID 40589683, 2025). "In our study, NF1-specific intracranial findings were detected in all patients (100%), although only one (20%) out of five children with CNV investigated by head MRI had an optic pathway glioma." (PMID 39857730, 2025). "In a study comparing patients with NF1 and optic pathway gliomas who received radiation therapy with those who did not, the relative risk of developing secondary malignancies was 3.04 (95% confidence interval (CI): 1.29-7.15) in the irradiated group." (PMID 41216086, 2025). "This is why, despite the fact that MMS was usually described as a consequence of cranial radiation therapy for NF1-related optic pathway glioma, the majority of cases have been reported as a primary manifestation of NF1 even in the absence of previous radiotherapy." (PMID 33921292, 2021). "Indeed, irradiated F1 mice in our mouse models do not develop CNS tumors, despite the fact that optic pathway gliomas (OPGs) are a type of CNS tumor that arises in 15–20% of children with NF1." (PMID 26000738, 2015).